PVT1 (Pvt1 oncogene)
Diseases named in the same sentence as PVT1 in open-access papers (continued):
Sharing a sentence is not in itself a finding about the gene and the disease.
tumor (continued). "To study whether combined inhibition of PVT1 and YAP1 has stronger anti-tumor activity in EAC, we conducted in vitro and in vivo experiments using PVT1 and YAP1 specific ASOs." (PMID 31601234, 2019). "Furthermore, we demonstrated, for the first time, that there is mutual regulation of PVT1 and YAP1 in EAC cells and that co-suppression of PVT1 and YAP1 by their specific ASO led to more effective suppression of EAC tumor growth in vitro and in vivo." (PMID 31601234, 2019). "In vitro and in vivo assays demonstrated that inhibition of PVT1 achieved by PVT1 ASOs could inhibit EAC cell proliferation, invasion, reduced CSC-related characteristics, and delayed tumor growth." (PMID 31601234, 2019). "Furthermore, PVT1 downregulates miR-31 to enhance the expression of cyclin-dependent kinases 1 (CDK1) and facilitates tumor cell proliferation, migration, and invasion." (PMID 31380270, 2019). "Our data showed that the ASOs, specific to PVT1 or YAP1, could achieve significant anti-tumor effect in vitro and in vivo." (PMID 31601234, 2019). "With the intersection of these 53 candidate lincRNAs with relative HCC genomic gains and the 1082 lincRNAs upregulated in the TCGA cohort of 50 paired HCC tissues and adjacent non-tumour (NT) tissues, four lincRNAs were identified, namely, LINC01138, PVT1, RP11-14N7.2 and RP11-30J20.1." (PMID 29679004, 2018). "Data from TCGA demonstrated that PVT1 expression was up-regulated in CCRCC tissues compared to normal tissues (534 tumor tissues and 72 adjacent non-tumor tissues)." (PMID 29254209, 2017). "By creating mice models carrying one extra copy of either MYC alone or the region co amplified with MYC, including the PVT1 gene, Tseng and colleagues demonstrated that in these experimental settings only the combination of both MYC and PVT1 is able to drive neoplasia." (PMID 28704924, 2017). "The level of PVT1 was detected in patient’s tumor tissue or circulating blood by RT-PCR; and the negative control was adjacent noncancerous tissue or healthy serum." (PMID 29088881, 2017). "Additionally, PVT1 overexpression also increased the expression of BMI1, ZEB1 and ZEB2 in xenograft tumor derived from 786-O cells." (PMID 29156724, 2017). "Also, in the animal experiments, PVT1 overexpression increased the expression of BMI1, ZEB1 and ZEB2 in xenograft tumor derived from 786-O cells." (PMID 29156724, 2017). "In this case, PVT1 was able to directly interact with miR‐30d‐5p, resulting in a competitive binding that decreased miR‐30d‐5p abundance and relieved the repression mediated by this miRNA on the downstream target RUNX2, an oncogene related to tumor growth and metastasis." (PMID 36366788, 2023). "Because subcutaneous tumor animal models are not suitable to assess tumor metastasis, we examined whether PVT1 KD retained the CSCs ability to develop HNSCC and metastasize by a mouse orthotopic HNSCC model." (PMID 36894542, 2023). "However, lncRNA PVT1 expression was not correlated with age, sex, tumor location, tumor size, or pathological grade." (PMID 32960485, 2021). "We further evaluated the effects of PVT1 ASOs on tumor cell invasion capacity using the transwell invasion assay and found that the number of invading cells was dramatically reduced when GA0518 cells were treated with PVT1 ASO#5 and PVT1 ASO#6 in a dose-dependent manner." (PMID 33076512, 2020). "Indeed, the proportion of CD4+ IFN-γ+ T helper 1 and CD8+ IFN-γ+ cytotoxic T lymphocytes was increased in tumor tissues (the latter also in the draining lymph nodes) of mice injected with G-MDSC lacking PVT1 expression." (PMID 32228602, 2020). "Furthermore, both transient and stable overexpression of PVT1 exon 9 in a nontumorigenic prostate epithelial cell line induced increased cell proliferation and migration, which are characteristics of the tumor phenotype." (PMID 31766781, 2019).
tumor (continued). "On the other hand, even if no increase in tumor formation was found in mice carrying a single extra copy of PVT1 only, PVT1 may have oncogenic properties also independently of MYC." (PMID 28704924, 2017). "Furthermore, research in the mechanism found PVT1 could target genes such as LASP1, FOXM1, RSPO1, p15, p16, EZH2, TSHR, and NOP2 to promote tumor cell proliferation, migration and invasive capability in vitro." (PMID 29088881, 2017). "PVT1 competitively regulated 42 and 9 mRNAs in the tumor and normal state respectively." (PMID 27580177, 2016). "In addition, MYC CNA was found in older individuals (p = 0.0007), which may be supportive of amplification at the MYC/PVT1 locus in tumor progression rather than initiation." (PMID 36139061, 2022). "Moreover, the observation that PVT1 is highly expressed in the T cell lineage and that circPVT1 levels are reduced in lymphocytes from SLE patients suggest novel potential direct implications of either the linear and the circular isoform in the T cell-mediated anti-tumor response." (PMID 32228602, 2020). "Since MYC depends on PVT1 in its ability to drive malignant transformation and is itself difficult to target because it lacks enzymatic activity, several groups have speculated about the validity and feasibility to target PVT1 to weaken or inhibit MYC in tumor cells." (PMID 33134177, 2020). "ETS1, though not in our list of significantly differentially expressed gene across all tumor types, regulates at multiple levels: at the level of E2F1, FOXM1 and PVT1, but due to its negative immunoreactivity in all tumor types, it may be doing so at gene/mRNA level." (PMID 30809433, 2019). "The lncRNA PVT1 and predicted target SERPINI1 (serpin peptidase inhibitor-clade I (neuroserpin)-member 1) were upregulated in OvCa cell lines and tumor tissues, unlike the downregulated tumor-suppressive miR-543." (PMID 33238475, 2020). "Unlike the well-characterized oncogenic long noncoding RNA PVT1, which is coamplified with MYC and enhances its stability, MYC-AS1 is epigenetically silenced and functions as a tumor suppressor through an RNAi mechanism, revealing a distinct layer of MYC regulation." (PMID 41190324, 2025). "Notably, while the oncogenic potential of the MYC-adjacent lncRNA PVT1 is well-established, the existence and functional significance of a MYC-specific antisense transcript acting as a tumor suppressor have not been elucidated." (PMID 41190324, 2025).
kidney disease (9 papers, 2013 to 2024). "As the first lncRNA that has been demonstrated to be related to kidney diseases, plasmacytoma variant translocation (PVT1) was confirmed to have a close relationship with the occurrence and development of DN." (PMID 35130617, 2022). "Zhang-Suo Liu at Zhengzhou University, China, and co-workers examined the role of a long noncoding RNA molecule known as PVT1, which has been recently associated with kidney disease." (PMID 31371698, 2019). "PVT1 is the first long non-coding RNA that has been associated with kidney disease." (PMID 24204837, 2013). "PVT1 is the first and, so far, the only, lncRNA that has been associated with kidney disease." (PMID 24204837, 2013). "LncRNAs (including plasmacytoma variant translocation 1 [PVT1], and metastasis-associated lung adenocarcinoma transcript 1 [MALAT1]) are associated with the progression of kidney disease." (PMID 38542060, 2024). "In addition, it is noteworthy that by analyzing lncRNA studies performed on renal diseases, we can identify six lncRNAs involved in more than one type of renal disease, in particular PVT1, TUG1, NEAT1, MALAT1, XIST, and H19." (PMID 37190024, 2023). "The lncRNA plasmacytoma variant translocation 1 (PVT1; 1.9 kb) is linked to kidney disease and encodes many alternative transcripts but not a protein." (PMID 36618403, 2022). "Apart from PVT1, H19 is also expressed in the nucleus and is significantly increased in some diseased conditions, which has been reported to participate in renal diseases." (PMID 35130617, 2022). "Among these, PVT1 and XIST have a common mechanism on multiple kidney diseases, the first increasing the expression of extracellular matrix proteins through the TGFB and the second inducing apoptosis." (PMID 37190024, 2023).
hematological malignancies (7 papers, 2017 to 2025). "Furthermore, in preclinical models of hematological malignancies, the linear form of human plasmacytoma variant translocation 1 (PVT1) is overexpressed in myeloid-derived suppressor cells." (PMID 35464462, 2022). "Among the class of dysregulated long non-coding RNAs (lnc-RNAs), it is noteworthy to mention the Plasmacytoma variant translocation 1 (PVT1), due to its known association with oncogenic mechanisms in solid cancers and other hematologic malignancies." (PMID 40721648, 2025). "The role of PVT1-lncRNA in hematological malignancies highlights its involvement in disease progression and regulation of immune responses." (PMID 37486375, 2023). "Since PVT1 also acts as a cis regulatory lncRNA, the interaction between MYC and PVT1 in different hematological malignancies has to take place via a positive feedback loop." (PMID 33134177, 2020). "Overall, PVT1 participates in the pathogenesis of several types of hematological malignancies through regulating multiple processes, such as cell cycle, cell proliferation, and cell apoptosis." (PMID 31480503, 2019). "Recently, PVT1 oncogene has been explored to be crucial in the pathogenesis of hematological malignancies." (PMID 31480503, 2019). "It is necessary to determine the mechanisms of PVT1 activation in hematological malignancies." (PMID 31480503, 2019). "Therefore, extracellular PVT1 and especially circPVT1 may have a putative role in hematological malignancies." (PMID 32228602, 2020). "Due to their close proximity at the 8q24 locus, PVT1 and the oncogene MYC are often considered twin players and a positive interaction feedback loop has been demonstrated in other hematological malignancies." (PMID 40721648, 2025). "Due to their close proximity at the 8q24 locus, PVT1 and MYC are often considered tween players, and a positive interaction feedback loop has been demonstrated in solid tumors and in APL and MM, among hematological malignancies." (PMID 32228602, 2020).
digestive system tumors (6 papers, 2018 to 2025). "PVT1 expression is elevated in gastrointestinal tumors and correlates with poor patient prognosis." (PMID 32083000, 2020). "There is increasing evidence that lncRNA PVT1 is involved in the proliferation and differentiation of digestive system tumors and also in epithelial–mesenchymal transition (EMT); lncRNA PVT1 has great potential to facilitate the diagnosis and treatment of digestive system cancers." (PMID 36379920, 2022).
infection (6 papers, 2017 to 2024). The state of being infected such as from the introduction of a foreign agent such as serum, vaccine, antigenic substance or organism. "To assess the function of PVT1 in BRCA, we established a PVT1 stable overexpression cell line using lentivirus infection in MDA-MB-231 cells and tested the overexpression efficiency." (PMID 36941464, 2023). "Increased expression of NEAT1, MALAT1, EGOT, PVT1, MIAT has been also observed in infection with other viruses." (PMID 34940755, 2021). "Other lncRNAs (i.e., BANCR, GAS5, GSTT1-AS1, PVT1, RMRP, and SNHG15) increased at one or more time-points during infection; BANCR was highly increased in infected cells, but only at 24 h." (PMID 31547203, 2019).
cardiovascular diseases (5 papers, 2021 to 2022). "Previous research has reported that lncRNA plasmacytoma variant translocation 1 (PVT1) up-regulation is involved in pathogenesis of cardiovascular diseases." (PMID 34595225, 2021). "In cardiovascular diseases, PVT1 has been reported to modify the increase and migration of vascular endothelial cells." (PMID 35498004, 2022). "Previous studies have found that PVT1 is dysregulated in many diseases, such as cancer and cardiovascular diseases." (PMID 35498004, 2022). "However, a few recent studies have implied that PVT1 was involved in cardiovascular diseases." (PMID 35036445, 2022).
colorectal (5 papers, 2020 to 2023). "Another study revealed that Yin Yang-1(YY1), a multifunctional transcription factor, bound to the promoter region of PVT1 and motivated its transcription through the consensus YY1 motif to promote cell proliferation, migration and invasion in lung cancer." (PMID 31897242, 2020).
digestive system cancer (3 papers, 2019 to 2022). A primary or metastatic malignant neoplasm involving any part of the digestive system. "The expression of PVT1 is elevated in various digestive system cancers and is associated with poor prognosis." (PMID 34336125, 2021).
hematological cancers (2 papers, 2023 to 2025). "Plasmacytoma variant translocation 1 (PVT1) is an oncogenic lncRNA overexpressed in many solid tumors and some hematological cancers." (PMID 36831169, 2023). "In particular, our attention was attracted by the aberrantly expressed PVT1, which plays oncogenic roles (mainly due to increased copy number and overexpression) in several types of solid and hematological cancers." (PMID 40721648, 2025).
metabolic disorder (2 papers, 2019 to 2023). "LncRNA PVT1 is located at 8q24.21 of chromosome and has been previously reported in metabolic disorder." (PMID 37626330, 2023).
endocrine tumors (1 paper, 2025). "Recently, the lncRNA PVT1 was shown to support glycolytic flux and mitochondrial function in endocrine tumors at least in part, suggesting a similar role in TC pathophysiology." (PMID 41154428, 2025).
inflammation (1 paper, 2019). Aberrant reaction of the microcirculation characterized by movement of fluid and leukocytes from the blood into extravascular tissues. "However, the exact role of PVT1 in the occurrence and development of pulp inflammation and the underlying mechanism require further investigation." (PMID 31304055, 2019).
neurodevelopmental disorder (1 paper, 2025). A behavioral and cognitive disorder with onset during the developmental period that involves impaired or aberrant development of intellectual, motor, or social functions. "While we detail here the genetic and epigenetic mechanisms of Pvt1 ME and its functional consequence, there are several aME genes from our list that are associated with neurodevelopmental disorders, such as Grik3, Mettl5, Gap43, and Tubb3." (PMID 41223055, 2025).
PVT1 also shares sentences with these, for which no sentence is quoted: cardiomyopathy (3 papers); Hypertension (3); laryngeal squamous cell carcinoma (3); aortic aneurysm (2); Arthritis (2); benign tumors (2); brain tumor (2); cervical (2); chronic lymphocytic leukaemia (2); diabetic cardiomyopathy (2); endocervical adenocarcinoma (2); Fibroadenoma (2); follicular lymphoma (2); glomerulosclerosis (2); hypertrophy (2); injury (2); kidney cancer (2); laryngeal carcinoma (2); metastasis (2); myocardial infarction (2); myositis (2); neurodegenerative disease (2); psoriasis (2); serous adenocarcinoma (2); squamous cell carcinoma (2); arrhythmogenic right ventricular cardiomyopathy (1); ataxia telangiectasia (1); autism (1); autoimmune thyroid disease (1); B-cell neoplasm (1).
A further 74 diseases each share a sentence with PVT1 in 1 paper.